MTOR (mechanistic target of rapamycin kinase)
Diseases named in the same sentence as MTOR in open-access papers (continued):
Sharing a sentence is not in itself a finding about the gene and the disease.
tumor (continued). "The combination of AR antagonist bicalutamide with PI3K inhibitor GDC-0941 or the dual PI3K/mTOR inhibitor GDC-0980 reduced LAR xenograft tumor growth." (PMID 35768871, 2022). "Collectively, we demonstrated that the tumor suppressor role of glycosylated CGA-T1 in PDAC is associated with its negative regulation of autophagy through multiple pathways, including PI3K/Akt/mTOR and TP53INP2 pathways." (PMID 35521536, 2022). "The upregulation of FASN enhances lipogenesis in tumor cells, mainly through activation of the AKT/mTOR signaling pathway, thereby contributing to the immunometabolic switch in the tumor microenvironment and enhancing tumor growth and proliferation." (PMID 35127296, 2022). "miR-100 is downregulated in CS; it is considered a tumor suppressor that targets and inhibits the mammalian target of rapamycin (mTOR) signaling pathway, which is generally involved in tumor growth and metastasis." (PMID 35216464, 2022). "CircNRIP1 sponged miRNA-149-5p to promote GC progression by the AKT1/mTOR pathway that exerts a positive effect on EMT to promote tumor metastasis." (PMID 35170374, 2022). "Clinically, tumor tissue editing can adequately design tumor tissues, a prerequisite for efficacious use of mTOR inhibitors in refractory metastatic uveal melanoma or refractory Hodgkin’s disease with metronomic low-dose chemotherapy and a PPARα/γ agonist." (PMID 35814409, 2022). "The results indicated the up-regulation of mTOR signaling pathway in the group with high VCP expression, which is known to associate with tumor progression." (PMID 35562734, 2022). "We find that mTOR signaling pathway is upregulated in tRCC tumor tissues in both proteome and phosphoproteome levels, which indicates mTOR signaling is a potential therapeutic target." (PMID 36470859, 2022). "The mTOR signaling is a major compensatory pathway conferring drug resistance to anti‐tumor agents in an autonomous or non‐cell‐autonomous manner." (PMID 35587712, 2022). "It is well-known that PTEN acts as a tumor suppressor and hampers the activation of the proto-oncogenic mTOR pathway." (PMID 35503721, 2022). "Consistently, the in vivo anti-tumor effects of CUDC-907 accompanied by the downregulated expression of p-mTOR and LCN2 and upregulated expression of p-IRE1α and LC3B-II were evaluated in a xenograft mouse model." (PMID 35989326, 2022). "PI3K/AKT/mTOR inhibitors restore the anti-tumor immune effect of the body to some extent by blocking pathway activation." (PMID 36313041, 2022). "On the contrary, PEF-5 exposure negatively affected different processes involved in cellular remodeling and in regulation of the mTOR signaling pathway, known to be involved in tumor metabolism." (PMID 35328420, 2022). "Metformin, as an inhibitor of the mTOR pathway, therefore directly inhibits tumor cell proliferation and induces apoptosis and cell cycle arrest in vitro." (PMID 36547172, 2022). "Next, we treated tumor slices prepared from two different AR-positive LuCaP models to mTOR inhibitors and mitochondrial metabolism." (PMID 35406510, 2022). "Expression of activated MEK1, activated AKT, activated mTOR or activated STAT3 all also reduced tumor cell killing by the drug combination, with expression of activated STAT3 trending towards being the most protective." (PMID 35136485, 2022). "Further studies in murine and human T-cell lymphomas demonstrated that rapamycin suppressed tumor growth, decreased mTOR activity, and reduced S6K and S6 phosphorylation." (PMID 35163615, 2022). "A phase I study evaluated Palbociclib in R/M HNSCC safe with tumor responses, and in vitro experiments combined with an mTOR inhibitor show promising anti-tumor effects." (PMID 36555474, 2022). "It is well known that FBXW7 serves as a tumor suppressor that promotes ubiquitination of a wide range of oncoproteins for proteasomal degradation, including mTOR." (PMID 35847937, 2022).
tumor (continued). "Some of the methods suggested to overcome drug resistance are a reactivation of the PI3K signaling pathway in combination with parallel pathways such as (but not limited to) the AKT/mTOR signaling network and manipulation of the tumor microenvironment." (PMID 35327484, 2022). "Hypoxia induces mTOR signaling and subsequent mitochondrial fragmentation that limits cytotoxic responses of tumor-infiltrating NK cells isolated from patients with liver cancer, or peripheral blood NK cells exposed to hypoxia ex vivo." (PMID 35414042, 2022). "Abnormal activation of the PI3K/Akt/mTOR pathway has been found to be one of the most important reasons for the development of tumor resistance to chemotherapy." (PMID 35684449, 2022). "It is well known that AMPK has a key role in intracellular energy homeostasis and it is believed that AMPK can inhibit tumor cell growth through the suppression of the mTOR pathway." (PMID 36551653, 2022). "MiR-221 has been reported to downregulate some tumor suppressor pathways such as PTEN/Akt/mTOR signaling and thus promote chemoresistance of BC cells." (PMID 36293478, 2022). "In vitro, cells expressing constitutively active vGPCR have high levels of activated Akt, inactivated TSC2 (a tumor suppressor which is inactivated by Akt), and activated mTOR." (PMID 35806208, 2022). "The AKT/mTOR signaling pathway has been reported to regulate not only tumor cell migration, but also tumor cell proliferation." (PMID 36551160, 2022). "We also observed an enrichment of smoothened receptor pathway signatures in the mTOR-resistant tumor." (PMID 36304922, 2022). "BIRC5 is positively regulated by the AKT/mTOR pathway to inhibit autophagy and apoptosis and promote tumor cell survival." (PMID 36713522, 2022). "The use of rapamycin in xenograft animal models has been shown to significantly reduce tumor growth, indicating that mTOR is a promising drug target for CTCL therapy." (PMID 35163615, 2022). "After detecting the inhibitory effect of FJD on tumor tissues, we further detected the changes of proteins related to the Bcl-2 family and the PI3K/AKT/mTOR/NF-κB signaling pathway in tumor tissues." (PMID 35281608, 2022). "In particular, PI3K and mTOR are known to be involved in SSc dermal fibrosis and have demonstrated an active role in tumor cell proliferation in BC." (PMID 36556228, 2022). "Autophagy controls tumor progression through MTOR inhibition, which activates CD8+ T cell differentiation to generate cytotoxic T lymphocytes (CTLs) but inhibits T cell differentiation into helper T cells." (PMID 36497321, 2022). "The AKT/mTOR signaling pathway is abnormally activated in a variety of human tumors, and plays an important role in tumor cell proliferation, survival, apoptosis, angiogenesis, metastasis, and resistance to radiotherapy and chemotherapy." (PMID 35152838, 2022). "KD can affect tumor cell growth by lowering insulin and IGF-1 levels, thereby reducing receptor tyrosine kinase-dependent signaling pathways such as PI3K-Akt-mTOR for tumor cell proliferation and tumor growth." (PMID 36432618, 2022). "mTOR is a serine/threonine protein kinase, whose abnormal activation is very general in malignant cells, resulting in tumor initiation and progression." (PMID 36588796, 2022). "In the WES samples, we detected somatic mutations in known PCa genes, including KMT2D, MTOR, SPOP, and PIK3R1, indicating tumor content in tissues assessed by single-cell analysis." (PMID 35013146, 2022). "To analyze MTOR mutations in CRC, we collected frozen tumor tissues from 48 patients with CRC and conducted whole-exome sequencing of MTOR genes." (PMID 35883111, 2022).
tumor (continued). "Nevertheless, several cellular processes, cytokines, and signaling pathways, especially the mTOR pathway, have been identified as key regulatory contributors of dormancy in disseminated tumor cells." (PMID 36436127, 2022). "Upon the comparison of Ku-0063794 and rapamycin, the number of tumor spheroids was decreased after treatment with Ku-0063794, indicating that a more complete inhibition of mTOR with the ATPase-competitive inhibitor prevents colony formation." (PMID 36551683, 2022). "Studies have shown that PI3K/AKT/mTOR pathway inhibitors are effective in suppressing tumor progression." (PMID 35281113, 2022). "In support of this, the authors showed that a mutation (D412G) in the PH domain of Sin-1 isolated from patients disabled its interaction with the catalytic domain of mTOR so as to activate mTORC2 and increase cell proliferation and tumor formation." (PMID 35955931, 2022). "The abnormal activity of CDKs and the activation of the PI3K/AKT/mTOR pathway are both factors contributing to tumor growth, and the inhibition of both generally needs to be carried out simultaneously." (PMID 36530984, 2022). "It directly targets PIK3CD and inhibits the migratory and invasive capacity of tumor cells via PI3K-Akt-mTOR cascade." (PMID 35659780, 2022). "In PT CRC cells, a single treatment with oxaliplatin caused a decrease in both the Akt/mTOR signaling pathway and AMPK phosphorylation, inducing tumor-suppressive autophagy and anticancer effects." (PMID 36359211, 2022). "At present, studies have found that activation of the PI3K/Akt/mTOR signaling pathway can inhibit the ferroptosis of tumor cells through lipid production." (PMID 36414988, 2022). "Suppressing the mTOR pathway can inhibit tumor growth by reducing cell proliferation and inducing apoptosis and autophagy, eventually reversing progestin resistance." (PMID 36551694, 2022). "Its downstream molecule mTOR can accelerate the formation of tumor stem cells, leading to tumor progression and relapse." (PMID 35299895, 2022). "Anti-VEGF can increase tumor radiosensitivity by blocking angiogenesis, inducing apoptosis in vascular endothelial cells, and activating the mTOR pathway to inhibit radiation-induced autophagy." (PMID 36036010, 2022). "Mechanistically, SLC6A14 was demonstrated to regulate the expression and phosphorylation of Akt-mTOR, which mediates the promoting tumor growth function of SLC6A14." (PMID 35907820, 2022). "The von Hippel-Lindau mutated tumor suppressor gene can activate HIF-1 via Akt-kinase and the PI3K/AKT/mTOR pathway." (PMID 36568220, 2022). "The proliferation of CRC cells can be disrupted by reducing the phosphorylation level of eIF4E-binding protein 1 (4EBP1), which is a tumor suppressor protein activated by mTOR." (PMID 35883111, 2022). "The PI3K/Akt/mTOR signaling pathway is a prominent intracellular signaling pathway that plays an important role in tumor cell growth and proliferation." (PMID 36096830, 2022). "Some circRNAs, such as hsa_circ_0079929, function as tumor regulatory factors through the Akt-mTOR axis, but the detailed mechanisms are unclear." (PMID 36142352, 2022). "The higher activity of mTOR in tumor-bearing mice is correlated to better efficacy of everolimus, underpinning the significant impacts of circadian rhythm of mTOR signaling on the antitumor therapies." (PMID 35515121, 2022). "The functional role of PI3K/AKT/mTOR signaling pathway in tumor progression and resistance to chemotherapeutic agents and the interconnectivity between SOX2 and PI3K/AKT have been previously proposed." (PMID 35309116, 2022). "Amino acid transporters play fundamental roles in multiple metabolic processes, including mTOR activation, energy metabolism, nutritional stress, and tumor progression." (PMID 35229720, 2022). "Abnormal activation of the PI3K/AKT/mTOR pathway has a key role in biological behaviours, such as proliferation, migration, invasion, and apoptosis of tumour cells." (PMID 35840921, 2022).
tumor (continued). "mTOR also alters glucose availability in tumor cells by regulating glucose uptake and glycogenolysis." (PMID 35244142, 2022). "Together, the results identified tumor-derived redHMGB1 as a priming signal to drive TLR4/mTOR/Bcl6-mediated trained immunity in TAMs." (PMID 36542153, 2022). "Located in chromosome 10, PTEN is a tumor suppressor gene involved in apoptosis, and cell cycle regulation via the mTOR pathway." (PMID 36011051, 2022). "Many studies have shown that the addition of inhibitors of the PI3K/AKT/mTOR pathway can effectively enhance tumor therapy." (PMID 36046833, 2022). "Recently, mTOR inhibitors in combination with anti-PD-1 have been reported to provide more durable and synergistic tumor regression than that by either agent alone." (PMID 35831271, 2022). "Overactivation and dysregulation of the mTOR pathway, which are caused by TSC1 or TSC2 abnormalities, promote tumor formation." (PMID 35359647, 2022). "PI3K/Akt/mTOR signaling in tumor cells mediates chemoresistance in the tumor microenvironment by shielding immune responses and activating multiple survival signaling pathways in human cancers." (PMID 36052124, 2022). "Protein profiles of PDM samples covered signaling pathways such as for cell cycle, DNA damage response, apoptosis, chromatin regulation, MAPK/RTK, PI3K/AKT with mTOR, Wnt and NFκB, as well as OvCa tumor/stem cell markers." (PMID 35740561, 2022). "LKB1 is now recognised as a tumour suppressor that acts through the mTOR pathway by inhibiting the activation of important proliferative oncogenes such as CCND1/CD1 and Myc." (PMID 35954497, 2022). "The tumor-suppressor miRs involved in the suppression of the mTOR pathway are miR758-3p, miR-142, miR-199b-5p, miR-187, miR-497, miR-99a, miR-592, miR-296-5p, miR-139-5p, miR-15b-5p, miR-345 and miR-223." (PMID 35625573, 2022). "Both PI13K and AKT are activated by interleukin (IL-12, I-L15), oncogenes, vascular endothelial growth factor (VEGF), and cytomegalovirus, which activates mTOR leading to the proliferation of lymphocytes, tumor cells, cytomegalovirus, and endothelial cells." (PMID 35265364, 2022). "The mTOR inhibition or activation of the type III PI3K complex can initiate the autophagic process of tumour cells." (PMID 36042213, 2022). "Studies have shown that inhibiting mTOR signaling can destroy angiogenesis, induce apoptosis and autophagy, and also block tumor cell progression." (PMID 35437508, 2022). "The resultant depletion of extracellular glucose causes dysfunction of tumor-infiltrating T cells and suppresses antitumor immunity, and PD-L1 expression by tumor cells promotes glycolysis through constitutive activation of the Akt/mTOR pathway." (PMID 34275008, 2022). "Immunohistochemical (IHC) analysis revealed that the anti-tumor efficacy of combined treatment with shNOP56 and rapamycin was paralleled by marked decrease of mTOR activity (p-AKT, p-mTPOR, p-S6) and increase in apoptosis (Caspase-3) in the residual tumors." (PMID 35039048, 2022). "It’s well known that activating mTOR signalling can enhance tumour proliferation and progression via distinct mechanisms, including the enhancement of angiogenesis, glyolytic and lipid metabolism, and inhibition of autophagy." (PMID 35814454, 2022). "Neoadjuvant targeted therapies, such as VEGFR or mTOR inhibitors, have been shown to reduce tumor thrombus levels and potentially make thrombectomy more feasible." (PMID 35361264, 2022). "Similar results indicate that stimulating the C/EBPβ pathway by mTOR promotes tumor growth and immune suppression." (PMID 36430972, 2022). "Treatment with AKT and mTOR inhibitors was able to decrease the tumor burden of mice and significantly increase the probability of survival in the treatment group (p < 0.0001)." (PMID 35454789, 2022). "After tumor establishment, the mice were treated every 2 days with either 2 mg/kg mTOR inhibitor rapamycin or vehicle." (PMID 35437691, 2022).
tumor (continued). "We first found that AKT and mTOR were highly expressed in OC tissues by RT-qPCR, and their levels were gradually increased with tumor progression (all P < 0.05)." (PMID 35672774, 2022). "For example, ammonia produced by glutamine metabolism promotes autophagy in tumors, and glutamine metabolism inhibits autophagy in tumor cells by activating the mTOR pathway." (PMID 35897036, 2022). "P62 subsequently acts as a crucial regulator of HCC development by promoting antioxidant pathways (NRF-2), cell proliferative mechanisms (mTOR), and inflammatory conditions (NF-kB), thus contributing to tumor cell growth." (PMID 35159028, 2022). "Study found that reduced dietary protein inhibits tumor growth and also inhibits mTOR activity in tumor." (PMID 35761356, 2022). "Based on the xenograft tumour results, real-time qPCR and Western blotting were performed to re-examine the tumour repressor PTEN to mTOR signaling pathways." (PMID 36142252, 2022). "Taken together, both everolimus and octreotide can inhibit tumor growth through the mTOR signaling pathway." (PMID 36248960, 2022). "Cox regression multivariate analysis show IL-7R, mTOR, and tumor stage were independent predictors of survival." (PMID 35778432, 2022). "Up-regulating mTOR signaling can promote tumor growth and progression through a variety of mechanisms." (PMID 35477450, 2022). "EGFR and PDGFRα downregulation as well as Akt-mTOR inactivation was detected in TN-treated HeLa xenograft tumor tissues." (PMID 39282148, 2022). "The main aim of this review is to present PC incidence, risk factors, tumor microenvironment development, and PI3K/AKT/mTOR dysregulation and inhibitors used in clinical, in vivo, and in vitro studies." (PMID 36077529, 2022). "The PI3K/AKT/mTOR pathway is involved in cell growth, apoptosis regulation, and glucose metabolism, among many other pro-tumor processes." (PMID 35806358, 2022). "Overall, the combination of in vitro and in vivo data confirms that blockade of the PI3K/mTOR pathway in combination with mGluR1 or HER inhibition negatively affects tumor progression." (PMID 35086953, 2022). "Previous studies suggest that PNCK promotes tumor growth by suppressing PI3K/AKT/mTOR signaling in NPC." (PMID 35535310, 2022). "Others linked mitochondrial dysfunction to the inhibition of tumor progression through disturbing the autophagic machinery, which interacted with NAD+ metabolism through AMPK and mTOR signaling pathways." (PMID 35869047, 2022). "Tumor-specific resistance mechanisms include mutations in pathways such as the interferon gamma pathway, the MAPK pathway, and the PI3K/AKT/mTOR pathway." (PMID 36291789, 2022). "Among these drugs, the mTOR inhibitor rapamycin and the double tyrosine kinase inhibitor lapatinib have been shown to inhibit the growth of tumor cells by promoting cell iron death." (PMID 35155251, 2022). "The PI3K/Akt and mTOR signaling pathways are activated by receptor tyrosine kinases that lead to tumor cell growth and proliferation." (PMID 36106139, 2022). "At the same time, the molecular mechanisms of apoptosis has also been confirmed to play an important role in the anti-tumor effect of PI3K/AKT/mTOR pathway, by activating various apoptotic signals or inhibiting survival signals." (PMID 35311154, 2022). "In particular, activation of Akt/mTOR signaling promotes EMT, which is closely associated with tumor invasion." (PMID 36380016, 2022). "PFE-treated mice show decreased activities in MAP kinase cascades, mammalian target of rapamycin (mTOR) cascades, and NF-κB, inhibiting tumor cell proliferation and angiogenesis." (PMID 36362994, 2022).